STAT3 (signal transducer and activator of transcription 3)
Diseases named in the same sentence as STAT3 in open-access papers (continued):
Sharing a sentence is not in itself a finding about the gene and the disease.
tumor (continued). "Tumor tissues were further analyzed by immunohistochemistry (IHC) for STAT3 and Ki-67." (PMID 24025152, 2013). "Many factors overexpressed in the tumor macro- and microenvironments promote STAT3 activation." (PMID 24339824, 2013). "Its downstream key molecules STAT3 is expressed abnormally and activated in multiple tumor tissues." (PMID 23590999, 2013). "We then prepared RNAs from the tumor tissues with differential numbers of p-STAT3-positive B cells." (PMID 23734190, 2013). "In addition, the STAT pathway appears activated in approximately 20% of the tumor with nuclear translocation of p-STAT3 (Tyr 705)." (PMID 23922674, 2013). "In growing tumors, Stat3 is persistently activated in tumor-infiltrating B cells." (PMID 23734190, 2013). "The tumor microenvironment is composed of tumor cells, macrophages, and immunocytes etc. where the interactions between these cells involves their secreted cytokines and consists of a free-forward loop with persistent activation of STAT3 enabling promotion of tumor growth." (PMID 23379788, 2013). "Thus, STAT3 activation increases the number of surviving tumor cells that invade distant potent organs to form secondary tumor." (PMID 24199193, 2013). "Interestingly, tumor-bearing mice with STAT3−/− hematopoietic cells possess a significant reduction in the number of tumor-infiltrating Treg." (PMID 23720663, 2013). "Since B cells are commonly present as aggregates with other immune cells, B cells may contribute to a network with other cells to promote tumor angiogenesis in a STAT3-dependent manner." (PMID 23734190, 2013). "The survival of tumor cells can become dependent on the continuous activity of Stat3 or Stat5." (PMID 24276378, 2013). "Thus, developing agents that inhibit STAT3 is a rapidly emerging goal for eventually designing a new class of compounds that inhibit Treg development, function and/or tumor-infiltration." (PMID 23720663, 2013). "From the data presented above, we hypothesize that within the tumor microenvironment, NF-κB in other cell types is likely activated and thus contributes to STAT3 activation and/or tumor growth in that capacity." (PMID 24244348, 2013). "Thus, constitutive deletion of Stat3 in the basal layer of epidermis inhibited TPA-induced epidermal hyperproliferation during tumor promotion." (PMID 23577258, 2013). "It has been reported that aberrant STAT3 activation promotes uncontrolled tumor cell growth and survival through multiple mechanisms, including increased expression of oncogenes, such as c-myc, Skp2, and cyclin D1, as well as antiapoptotic proteins, including Bcl-2, Bcl-xL, Mcl-1, and survivin." (PMID 24386318, 2013). "Additionally, Icaritin inhibited tumor angiogenesis, potently suppressed STAT3 activation, and significantly reduced RCC tumor growth in vivo." (PMID 24324713, 2013). "We also determined whether the tumor milieu-induced, B cell-mediated tube formation was at least in part due to elevated Stat3 activation in B cells." (PMID 23734190, 2013). "STAT3 activation is rapid and transient in normal cells; however, in cancer cells STAT3 is constitutively activated, resulting in imbalance between cell proliferation and apoptosis, and uncontrolled tumor angiogenesis." (PMID 23800091, 2013). "Given that STAT3 is constitutively activated in diverse cancers, including RCC, we assessed whether Icaritin-induced tumor cell death was associated with STAT3 inhibition." (PMID 24324713, 2013). "Finally, to inhibit both tumor cell NF-κB and global STAT3, mice received the combination of Dox supplemented food and AZD1480 treatment." (PMID 24244348, 2013). "Importantly, over-expression of STAT3 in miR-124-transfected CRC cells completely rescues the reduction in tumor size when growing in vivo." (PMID 23940556, 2013). "In murine tumor model, STAT3 inhibitors have been shown to augment anti-tumor immunity." (PMID 23755373, 2013).
tumor (continued). "More and more evidences demonstrate the significance of STAT3 in oncogenesis and tumor development." (PMID 23590999, 2013). "Blocking STAT3 signaling through STAT3 antisense oligonucleotides or RNA interference may induce growth arrest and apoptosis in various tumor types." (PMID 24179517, 2013). "Evidence that dysregulated STAT3 was sufficient for neoplastic transformation was provided by experiments which showed that constitutively active forms of STAT3 (phosphorylated STAT3) were capable of promoting malignant transformation in fibroblasts and tumor formation in mice." (PMID 24376586, 2013). "However, in vivo, both NF-κB and STAT3 appear to be activated in response to multiple stimuli in the tumor microenvironment, and single agent therapies prove less effective." (PMID 24244348, 2013). "A multitude of signaling events by STAT3 may converge to enhance tumor progression with increased resistance against chemotherapeutic agents." (PMID 24025152, 2013). "Similarly, Nielsen and coworkers showed that AG490 blocked the constitutive activation of STAT3 and inhibited both spontaneous and interleukin 2-induced growth of mycosis fungoides tumor cells." (PMID 24199193, 2013). "In cancer cells, STAT3 plays important roles in tumor growth and progression." (PMID 23940556, 2013). "Protein tyrosine phosphatase delta (PTPRD) is a tumor suppressor that inhibits STAT3 activation." (PMID 23800680, 2013). "Therefore, we suggest activation of STAT3 signaling and angiogenesis after irradiation was reported to be responsible for resistance to treatment and tumor regrowth after irradiation triggered by IL-6." (PMID 23561329, 2013). "In this study, we examined if berberine may suppress STAT3 activation in NPC grown as xenografted tumor in nude mice." (PMID 24380387, 2013). "Moreover, we established that GSPE is a promising substance for treating immunologic diseases related with STAT3 including several metabolic diseases, inflammatory diseases and neoplasms in the future." (PMID 24223854, 2013). "The Stat3 signaling pathway may impact tumor metastasis via regulation of several types in this process." (PMID 23340652, 2013). "After phosphorylation, STAT3 forms a dimer which is then translocated to the nucleus to regulate the expression of several genes leading to the induction of a series of events including tumor cell growth, survival and metastasis." (PMID 23593315, 2013). "The expression of STAT3 in AFPGC plays an important role in tumour invasion and prognosis." (PMID 23382965, 2013). "Interestingly, here we demonstrate that this phenomenon is not limited to MSC or tumor cells, as also normal fibroblasts can similarly induce STAT3 phosphorylation upon interaction with APCs." (PMID 24073274, 2013). "In addition, STAT3 is constitutively activated both in tumor cells and in immune cells confined in tumor microenvironments, and STAT3 inhibits the expression of mediators necessary for mounting an immune response against the tumor cells." (PMID 23977103, 2013). "In addition to promoting endothelial cell migration, Stat3 activation intrinsic to B cells was critical for B cells’ own migratory ability to tumor-secreted chemoattractants (left)." (PMID 23734190, 2013). "IL-17 then promotes tumor growth through IL-6 induction, which in turn activates Stat3 in tumors." (PMID 24453427, 2013). "The tumor sections in the control group revealed 75% ± 12.6 of positive staining of p-STAT3 while only around 12.4 ± 8.6 and 5.4 ± 4.5% of cells were stained positive for p-STAT3 in the treatment groups injected with 5 mg/kg and 10 mg/kg of berberine respectively (p <0.05)." (PMID 24380387, 2013). "Our results also suggest that constitutively active STAT3 in these cancer stem-like cells enhances tumor growth in mice, whereas STAT3 blockade by LLL12 directly suppresses MDA-MB-231 and SUM-159 ALDH+ cell growth in xenograft and mammary fat pad mouse models respectively in vivo." (PMID 24376586, 2013).
tumor (continued). "IL-17 then promotes tumor growth through Stat3 activation dependent on IL-6 induction." (PMID 24453427, 2013). "Although this study did not investigate downstream effects of resveratrol-induced STAT3 deacetylation, a recent report demonstrated that acetylated STAT3 methylates the promoter region of tumor suppressor genes and results in gene silencing that promotes tumour cell proliferation." (PMID 23372833, 2013). "Indeed, SOX4 is directly regulated by hsa-miR-335 in cancer progression, while hsa-miR-125b coordinates STAT3 regulation in the proliferation of tumor cells." (PMID 23782521, 2013). "Because myeloid cell STAT3 activity not only impacts immune regulation in the context of tumor, but also plays an important role in pre-metastatic tissue, the formation of myeloid clusters and the activation of STAT3 may affect patient prognosis." (PMID 23717691, 2013). "To ascertain that STAT3 is indeed the downstream mediator of miR-124’s inhibitory effect on cancer cell survival and in vivo tumor growth, we designed siRNA against STAT3 to specifically down-regulate STAT3 expression and seek to recapitulate the effect of miR-124 on CRC development." (PMID 23940556, 2013). "This could partially explain why the density of tumor-infiltrating B cells reflects the overall STAT3 activity in human tumor tissues in our study." (PMID 23734190, 2013). "It is possible that EGFR and STAT3, individually or as a pair, contribute to tumor progression." (PMID 24499623, 2013). "In NPC, one of our previous publications also showed that brief exposure of tumor cells with JAK/STAT3 inhibitor could efficiently suppress the tumor initiation in nude mice." (PMID 24380387, 2013). "Importantly, tumor-growth inhibition was correlated with p-STAT3 inhibition (left), as well as with the enhancement of SHP-1 activity in these drug-treated xenograft tumors (right)." (PMID 23938089, 2013). "Given the unique embryonic lethal phenotype of Stat3 targeting, tissue-specific knockout and inducible knockout strategies using the Cre-loxP system have been used to elucidate the role(s) of Stat3 in skin biology and skin carcinogenesis." (PMID 23577258, 2013). "Furthermore, in human tumor tissues as well as in mouse tumors, many of the angiogenic factors secreted by B cells are canonical STAT3 activators, implying a positive feedback loop in tumors." (PMID 23734190, 2013). "Enterotoxigenic bacteroides fragilis (ETBF), a human colonic commensal bacterium, can promote colonic tumorigenesis in APC mutant mice via Stat3 activation and Th17-cell polarization, and further blocking IL-17 or IL-23R can significantly reduce tumor formation in vivo." (PMID 24382972, 2013). "All these findings suggest JAK2/STAT3 pathway may play a crucial role in simvastatin-induced anti-tumor effects in RCC cells." (PMID 23690956, 2013). "In addition, EESP significantly inhibited the phosphorylation of STAT3 in tumor tissues, indicating its suppressive action on the activation of STAT3 signaling." (PMID 23800091, 2013). "Our studies provided the first evidence that AL may inhibit tumor angiogenesis and growth via blocking STAT3 activation, with the potential of a drug candidate for cancer therapy." (PMID 23848964, 2013). "It is possible that the increase in these cytokines in the extracellular media surrounding tumor cells might promote tumorigenesis by activating NFKb and/or STAT3 pathways." (PMID 23565217, 2013). "Finally, Icaritin significantly blunted RCC tumor growth in vivo, reduced STAT3 activation, and inhibited Bcl-xL and Cyclin E, as well as VEGF expression in tumors, which was associated with reduced tumor angiogenesis." (PMID 24324713, 2013). "However, STAT3 can also have a tumor suppressor function as shown recently for intestinal cancer, where it affects the activity of other members of the STAT family and the expression of cell adhesion molecules." (PMID 23915189, 2013).
tumor (continued). "Indeed, conditional deletion of STAT3 in colonic epithelial cells and in hepatocytes resulted in reduced tumor development in mice." (PMID 23940556, 2013). "PKCζ could be considered a tumor suppressor, though other studies have elucidated functional contributions of the connection of PKCζ to NF-κB and Stat3/IL-6 in carcinogenesis." (PMID 24062985, 2013). "While the opposing roles of PKCζ in both tumorigenesis and STAT3 activation in pancreas and lung may be explained by differences in the tissue type, they may also be due to cancer-specific roles for PKCζ in tumor initiation and maintenance." (PMID 24015205, 2013). "In addition to its multiple roles within the tumor cell, STAT3 can promote immunosuppression in a tumor-bearing host via its ability to induce the differentiation of early myeloid cells into that of a myeloid-derived suppressor cell (MDSC) phenotype." (PMID 22899991, 2012). "Moreover, as STAT3 is hyperphosphorylated in DC in the tumor environment or exposed to the tumor supernatants, leading to DC dysfunction, the use of AG 490 has been shown to be able to revert their dysfunction." (PMID 22412839, 2012). "In these examples, expression of SOCS3 may be a natural consequence of increased STAT3 activation and cytokine production by tumor cells." (PMID 23028842, 2012). "Most tumor-derived factors exert the inhibiting effects on differentiation and maturation of myeloid cells through signal transducer and activator of transcription 3 (STAT3) signaling pathway." (PMID 22481970, 2012). "This novel role of Stat3 in gap junction function may be an important regulatory step in progression of tumours that exploit such a pathway." (PMID 23244248, 2012). "In this study we sought to confirm their findings and investigate in vitro whether STAT3 integrates control of proliferation and the tumour microenvironment in ESFT tumors." (PMID 22315522, 2012). "Next, we evaluated the effects of M-HIFU on STAT3 activation using RM-9 tumor-bearing mice." (PMID 22911830, 2012). "Besides that, Stat3 inhibits the expression of IL-12 which is involved in anti-tumor responses via NK cell activation and Th1 induction." (PMID 22855687, 2012). "In the control (n=5) and bevacizumab-treated (n=6) groups at the time of treatment failure, STAT3-expressing cells could be seen at the leading edge of the corpus callosum, at the tumor margin and along the leptomeninges." (PMID 23013619, 2012). "Activation of NF-κB in tumor cells can produce ROS that further induces DNA damage and genomic instability, leading to the activation of pro-tumorigenic transcription factors, such as STAT3 and AP-1." (PMID 23227270, 2012). "Jak2 is a new target for tumor growth suppression due to its role in the activation of STAT3." (PMID 22792362, 2012). "First, reduction of p-STAT3 in the tumors directly inhibits tumor growth." (PMID 22911830, 2012). "Stat3 is constitutively activated in U266 cells and various primary tumors and tumor cell lines." (PMID 22279540, 2012). "In addition to the quantitative difference of p-STAT3 tumor expression between the control and the antiangiogenic therapy-treated group, there was a distinctive difference in the pattern of p-STAT3 expression." (PMID 23013619, 2012). "However, it is worth noting that two recent studies, performed in ApcMin/+ mice, showed STAT3 to exert opposite roles on colon carcinogenesis depending on the tumor stage." (PMID 23109839, 2012). "Here, we confirm that Stat3 is a promising pathway target regulating tumor growth." (PMID 22879872, 2012). "Since Stat1 and Stat3 show opposing patterns that promote or inhibit apoptosis, respectively, we examined the expression of anti-apoptotic Bcl-XL and pro-apoptotic pBad and Bax proteins in AT-101 sensitized tumor cells in the presence of ATC or aATC." (PMID 23185240, 2012).
tumor (continued). "Since IFNs promote the activity of STAT1 andSOCS1, but inhibits the activity of STAT3, it is theoretically feasible thatIFN-α and IL-24 may augment their anti-tumor activities." (PMID 22569271, 2012). "In this study, we found that PTPMeg2 is a tumor repressor preferentially dephosphorylating STAT3." (PMID 22394684, 2012). "Inhibition of STAT3 in tumor cells in which it is constitutively activated leads to cell death." (PMID 22423663, 2012). "These JAK kinases are known to modulate multiple STAT family members, including STAT1 and STAT3.These members of the signal transducer and activator of transcription (STAT) family of transcription factors have been implicated in transformation, tumor cell survival, invasion, and metastasis." (PMID 22537161, 2012). "It is therefore possible that, in at least a subset of lung tumors, STAT3 primarily controls pathway(s) that specifically affect taxane sensitivity, but does not significantly affect the function of genes directly involved in controlling tumor cell survival." (PMID 22723956, 2012). "We tested whether long-term Rac inhibition also blocks STAT3 activity in the explant tumour cultures." (PMID 22689141, 2012). "STAT3 is involved in tumor progression by inducing angiogenic factors such as VEGF." (PMID 22485142, 2012). "Tumor angiogenesis is enhanced as VEGF expression is up-regulated by increased STAT3 activity." (PMID 22485142, 2012). "It is feasible that theSG600-IL-24 virus mediates its anti-tumor activity via STAT3 inhibition." (PMID 22569271, 2012). "Antiangiogenic therapy-mediated induction of hypoxia within the tumor microenvironment could be directly responsible for activation of the STAT3 pathway and the chemoattraction of myeloid cells to the tumor via STAT3-mediated mechanisms." (PMID 23013619, 2012). "Neuropathological review indicated that the p-STAT3 nuclear expression was not only seen in the pleomorphic tumor cells, but also within cells with thin, elongate, nuclei with slender bipolar cytoplasmic processes that have the morphological characteristics of microglia, and in the endothelium." (PMID 23013619, 2012). "In the contrary, although Stat3 is generally growth promoting and in an activated form it can act as an oncogene, we show for the first time that Stat3 is actually required for gap junctional communication both in normal epithelial cells and in certain tumor cell lines that retain GJIC." (PMID 23244248, 2012). "Therefore, inhibiting or demolishing active STAT3 is of interest for both direct anti-tumor treatment and tumor specific immunotherapy." (PMID 22911830, 2012). "APE1 and STAT3 are upregulated and play important roles in cancer, suggesting that tumor cells may be ‘addicted’ to their effector functions." (PMID 23094050, 2012). "Importantly, we observed a four-fold improvement in the 30-day recurrence-free survival relative to docetaxel alone with the addition of the Stat3 inhibitor in the chemoresistant tumor model." (PMID 22879872, 2012). "Constitutively active STAT3 can up-regulate VEGF transcription leading to tumor angiogenesis." (PMID 22792362, 2012). "IL-22 may therefore play a role in tumor growth, cell differentiation and progression through STAT3-dependent and -independent pathways." (PMID 22922995, 2012). "Likewise, over expression of a constitutively active p-STAT3 mutant has been found to induce tumor growth in murine and in vitro studies." (PMID 22488042, 2012). "Moreover, aberrant STAT3 promotes invasion and metastasis, thereby contributing to tumor progression." (PMID 22911830, 2012). "Since STAT3 phosphorylation is highly related to tumorigenesis, we attempted to examine whether PTPMeg2 could affect tumor progression." (PMID 22394684, 2012). "In addition, targeted disruption of Stat3 in the skin demonstrated the role of Stat3 and follicular stem cells in tumor initiation." (PMID 22879872, 2012).